CHEK2 (checkpoint kinase 2)
Diseases named in the same sentence as CHEK2 in open-access papers (continued):
Sharing a sentence is not in itself a finding about the gene and the disease.
breast cancer (continued). "The authors estimated that 20% of CHEK2:c.1100delC carriers with the highest PRS had an estimated lifetime breast cancer risk of > 30%." (PMID 34285278, 2021). "The risk of developing breast cancer in CHEK2 mutation carriers is associated with family history and increases when the carriers have first- and second-degree relatives who are affected." (PMID 35127508, 2021). "We demonstrated PALB2 OR ≥ 6 and CHEK2 OR ≥ 4 for breast and breast–ovarian cancer, and found specific breast cancer pathology associations where a PALB2 PGV is present." (PMID 34113003, 2021). "Certain variants in CHEK2 are associated with increased breast cancer risk, with a cumulative lifetime risk ranging from 28% to 37%, depending on family history." (PMID 33800556, 2021). "Previously identified variants that modify breast cancer risk in CHEK2:c.1100delC carriers are also risk variants in the general breast cancer population." (PMID 34285278, 2021). "Our data demonstrated the identification of twenty distinct deleterious variants among fifty-two CHEK2 carriers with breast cancer." (PMID 33925588, 2021). "In the Netherlands a nationwide study recently started that will address the risk prediction, screening and therapy of breast cancer in women from CHEK2 c.1100del families." (PMID 33468213, 2021). "A possible association of ATM-BRIP1-PALB2 and a significant association of CHEK2 pathogenic/likely-pathogenic coding variants with multiple tumors, including bilateral breast cancer, was observed." (PMID 34299313, 2021). "Next are moderate-penetrance genes like CHEK2, causing a significant but limited increase in breast cancer risk." (PMID 34635169, 2021). "Until now in Poland, this approach has been applied for testing of founder BRCA1/2, PALB2, and CHEK2 mutations in association with breast cancer risk." (PMID 33670479, 2021). "CHEK2 is now commonly included in genetic tests for breast cancer predisposition and increasingly used to inform the clinical management of women who are identified to carry pathogenic variants." (PMID 33803639, 2021). "Cell-cycle checkpoint kinase 2 (CHEK2) is an established breast cancer predisposition gene whose protein plays an important role in cell-cycle checkpoint regulation and DNA damage repair." (PMID 33803639, 2021). "Another mutant CHEK2-H371Y detected in our study was confirmed as a breast cancer risk variant in 2011, for 4% of the total patients." (PMID 34630562, 2021). "It is well established that women who carry pathogenic CHEK2 variants have about a 3-fold increased risk of developing breast cancer." (PMID 33803639, 2021). "A meta-analysis of breast cancer risk associated with CHEK2 c.1100delC estimated an odds ratio (OR) of 2.7 (95% CI, 2.1–3.4) for unselected breast cancer cases and OR 4.8 (95% CI, 3.3–7.2) for women with a family history of breast cancer." (PMID 33803639, 2021). "Carriers of high risk CHEK2 variants are offered enhanced breast cancer surveillance, with the frequency and duration of enhanced screening guided by their family history." (PMID 34771713, 2021). "The carriers of truncating variants in CHEK2 that have a strong family history of breast cancer are offered high intensity surveillance, with annual mammograms between the ages of 40–60 years." (PMID 34771713, 2021). "Six individuals with breast cancer harboured risk factor variants in the ATM or CHEK2 genes, and if they had close relatives with breast cancer, they would have been offered clinical genetic testing according to guidelines." (PMID 34711244, 2021). "Herein, we have collected fifty-two breast cancer patients of Greek descent that have been identified as CHEK2 pathogenic variant carriers through germline genetic testing." (PMID 33925588, 2021). "We observed a correlation between the three truncating mutation in the CHEK2 gene (c.1100delC, c.444 + 1G > A and del5395(ex10-11del)) and male breast cancer in Poland (OR = 2.93: p = 0.02)." (PMID 34461861, 2021).
breast cancer (continued). "In the USA, the CHEK2/T470C variant has been reported in 1.2% of the population, while in Germany, the frequency was 2.2% in breast cancer cases and 0.6% in controls; and in Belarussian population, 5.7% in cases and 1.3% in controls." (PMID 33778923, 2021). "CHEK2 germline pathogenic variants predispose to breast cancer and possibly to other malignancies, with their spectrum and frequency being variable among populations." (PMID 33925588, 2021). "We recommend that a simple test for Polish founder mutations in BRCA1, BRCA2, PALB2 and CHEK2 should be offered to all male breast cancer patients in Poland." (PMID 34461861, 2021). "We found that the frequency of the 1100delC founder mutation in the CHEK2 gene to be higher in male breast cancer cases (1.8%) than in females with breast cancer (0.6%)." (PMID 34461861, 2021). "We estimated the age-specific cumulative risk of breast cancer for carriers of pathogenic variants in CHEK2 in a population-based case-control-family study." (PMID 33803639, 2021). "Genotyping of 42,671 invasive breast cancer cases and 42,164 controls from BCAC found evidence that both CHEK2 c.349A>G and c.538C>T were associated with increased breast cancer risk; OR 2.26 (95% CI, 1.29–3.95) and OR 1.33 (95% CI, 1.05–1.67) respectively." (PMID 33803639, 2021). "An example of this is the CHEK2 gene, wherein there are pathogenic variants that give rise to an increased risk for breast cancer but the extent of risks for other cancers is under debate." (PMID 34711244, 2021). "ATM and CHEK2 are recognized as the most common breast cancer susceptibility genes, and their attenuation is associated with BRCAness, namely phenocopies of BRCA1/2 defects." (PMID 35008774, 2021). "CHEK2 is associated with Li-Fraumeni syndrome, an autosomal dominant disorder that manifests as multiple malignancies, including soft tissue sarcomas and breast cancer, supporting causality." (PMID 34359575, 2021). "Among the fifty-two breast cancer patients, twenty distinct pathogenic/likely pathogenic CHEK2 variants were detected." (PMID 33925588, 2021). "Several studies have reported an association between CHEK2 variants and an increased risk, though with low-penetrance, for breast cancer." (PMID 33840814, 2021). "This study provides an overview of the spectra of CHEK2 pathogenic variants among Greek breast cancer patients, while sheds some light on the clinicopathological characteristics of these tumors." (PMID 33925588, 2021). "This study aimed to identify genetic loci that modify CHEK2:c.1100delC-associated breast cancer risk by searching for candidate risk alleles that are overrepresented in CHEK2:c.1100delC carriers with breast cancer compared with controls." (PMID 34285278, 2021). "It has been shown that CHEK2 heterozygotes with a family history of breast cancer have a two- to threefold increased risk of breast cancer, classifying it as a moderate risk variant." (PMID 33468213, 2021). "In this study, we used whole-exome sequencing of a CHEK2:c.1100delC positive cohort with familial breast cancer, to identify putative risk modifying alleles." (PMID 34285278, 2021). "The vast majority of them was diagnosed with premenopausal breast cancer, in line with two recent studies where the estimated breast cancer risk decreased significantly with increasing age for CHEK2 carriers." (PMID 33925588, 2021). "This has firmly consolidated CHEK2 as a bona fide breast cancer predisposition gene but information suitable for estimating age-specific cumulative risk (penetrance) has been lacking." (PMID 33803639, 2021). "We describe the first reported case of three concurrent pathogenic germline variants in BRCA1, BRCA2, and CHEK2 associated with inherited breast cancer in an individual." (PMID 33507482, 2021).
breast cancer (continued). "CHEK2 (cell-cycle-checkpoint kinase 2) is another important gene for breast cancer susceptibility, discovered after BRCA1/2." (PMID 34771512, 2021). "The common truncating allele of CHEK2 (1100delC) was associated with a 4.5-fold increased risk of the male breast cancer in the Scandinavian population." (PMID 34461861, 2021). "For example, an investigation of germline variants in 5,391 Slavic patients with breast cancer found 17 breast cancer patients in which two pathogenic variants were detected; 4 (1.4%) of these women were found to be CHEK2 and BRCA1 double heterozygotes." (PMID 33507482, 2021). "On the other hand, with the exception of the European founder allele CHEK2 c.1229delC (1100delC), distributions of breast cancer genes were similar for AA and EA cases." (PMID 33479248, 2021). "Important information for counselling these women includes knowing how breast cancer risk, due to having a pathogenic variant in CHEK2, changes over a woman’s lifetime." (PMID 33803639, 2021). "Deleterious germline CHEK2 variants have been associated with an increased risk of developing primarily breast cancer and colorectal cancer." (PMID 34513715, 2021). "In summary, our study defined ATM and CHEK2 as moderate risk genes for breast cancer in Chinese women." (PMID 34606182, 2021). "We conducted a population-based case-control-family study of pathogenic CHEK2 variants (26 families, 1071 relatives) and estimated the age-specific cumulative risk of breast cancer using segregation analysis." (PMID 33803639, 2021). "Case-control studies have estimated a 3-4-fold increased risk of breast cancer associated with pathogenic CHEK2 variants." (PMID 33803639, 2021). "CHEK2/T470C is associated with reduced DNA repair ability and increased cancer susceptibility, such as breast cancer, colorectal cancer and prostate cancer." (PMID 33778923, 2021). "In the present study we describe the CHEK2 variant spectrum, while depicting the histopathological characteristics and clinical outcomes of fifty-two Greek breast cancer patients who were CHEK2 carriers." (PMID 33925588, 2021). "CHEK2 is now included in routine gene panel tests for breast cancer susceptibility which has substantially increased the need to more precisely understand the breast cancer risks associated with rare genetic variants in this gene." (PMID 33803639, 2021). "CHEK2 c.1100delC is the most common protein-truncating variant in European populations and has been the focus of work that has estimated the magnitude of breast cancer risk associated with CHEK2 pathogenic variants." (PMID 33803639, 2021). "The 1100delC mutation in CHEK2 has been evaluated in several other studies and four of these showed an increased risk of male breast cancer." (PMID 34461861, 2021). "In the largest study of 715 male breast cancers the odds ratio associated with the 1100delC mutation in the CHEK2 gene was 3.8 (p = 0.002)." (PMID 34461861, 2021). "It has been shown that CHEK2 germline mutation carriers are at increased risk of developing female breast cancer with a predisposition to ER-positive disease and colon cancer." (PMID 35127508, 2021). "Aloraifi and colleagues performed a meta-analysis of protein-truncating variants in moderate-risk breast cancer genes in 2015 and cited only 12 out of 54 published CHEK2 analyses (22%) that had performed full gene scanning." (PMID 33322746, 2020). "For instance, the CHEK2 variant c.1100delC, which has been shown to increase breast cancer risk by 2-fold, is frequently found in northern European populations, but is rare in southern European populations." (PMID 33158149, 2020).
breast cancer (continued). "We found the adjacent p.P116L variant, described previously in a patient with sporadic cardiac sarcoma, in a patient with multiple melanoma and breast cancer, who also carried a large pathogenic CHEK2 deletion." (PMID 33050356, 2020). "All in all, germline CHEK2 mutations confer increased risk of the development of ER-positive breast cancer with an unfavorable prognosis and an increased risk of bilateral breast cancer." (PMID 33322746, 2020). "The CHEK2 variant conferred a risk increase for breast cancer with HR 2.19 (95% CI 1.91–2.51), p = 3.90 × 10−29), corresponding to a lifetime risk of 31.7% (95% CI 29.5–33.9%)." (PMID 33318493, 2020). "A prospective study had shown that in estrogen receptor–positive breast cancer, CHEK2*1100delC heterozygosity was associated with increased risk of early death, breast cancer–specific death, and risk of a second breast cancer." (PMID 33086730, 2020). "Breast cancer in the carriers of pathogenic germline CHEK2 mutations has several recurrently reported clinicopathological characteristics." (PMID 33322746, 2020). "The estimated lifetime risk of breast cancer for CHEK2 mutation carriers (mostly c.1100delC) differs according to family cancer history and ranges from 20 to 40% in women without and with a positive family breast cancer history, respectively." (PMID 33322746, 2020). "Only two carriers (0.24%) of CHEK2 mutations were identified in a recent analysis of 831 breast cancer patients from Shanghai." (PMID 33322746, 2020). "Certain mutations in the CHEK2 gene (c.1100delC and I157T) are associated with increased breast cancer risk, with a cumulative lifetime risk ranging from 28% to 37% depending on family history." (PMID 32733558, 2020). "Multivariate logistic regression analysis was used to quantify the risk of breast cancer in biallelic CHEK2 PV carriers and monoallelic carriers." (PMID 31993860, 2020). "In a recent meta-analysis, Akdeniz demonstrated an increased contralateral breast cancer risk for CHEK2* 1100delC carriers (RR 2.75, 95% CI 1.77–4.27)." (PMID 31935898, 2020). "Using a similar cohort of patients who underwent clinical hereditary cancer testing, our laboratory has previously shown that women with any PV in CHEK2 have approximately twofold greater risk of developing any breast cancer than PV-negative women." (PMID 31993860, 2020). "CHEK2 is a tumor suppressor regulating a cell cycle checkpoint and mutations in the gene confer an increased risk for breast cancer." (PMID 32471470, 2020). "Since the first studies, CHEK2 germline mutations have frequently been associated (in 85–90% of cases) with estrogen receptor positive (ER+) breast cancer subtypes." (PMID 33322746, 2020). "In consistence, missense or deleterious mutations in CHEK2 causing loss of its kinase function, though very rare, have been correlated with different types of cancers, particularly breast cancer." (PMID 32541902, 2020). "This case report focuses on the presentation, diagnosis, and management of breast cancer, as well as long-term cancer screening in the setting of CHEK2 mutation in a relatively young male patient." (PMID 32766014, 2020). "Mutations in CHEK2 have been associated with resistance to anthracycline-based chemotherapy in breast cancer patients, but further studies are needed." (PMID 32824581, 2020). "While initial studies associated CHEK2 germline mutations with a moderate breast cancer risk, later ones identified a much wider portfolio of cancer types in CHEK2 mutation carriers." (PMID 33322746, 2020). "Taking into consideration that CHEK2 variants have been previously associated with other types of cancer, such as breast cancer, we performed an additional microsatellite haplotype analysis of all carriers available at IPO-Porto." (PMID 33158149, 2020).
breast cancer (continued). "The breast cancer PRS strongly altered the risk of breast cancer in PALB2 and CHEK2 mutation carriers, substantially increasing the risk of breast cancer in women with a high PRS, and lowering the risk in women with a low PRS." (PMID 33318493, 2020). "Prophylactic contralateral mastectomy can also be recommended for breast cancer patients with pathogenic CHEK2 germline mutations." (PMID 33322746, 2020). "The patient is only 44 years old, and the lifetime risk of breast cancer in females with a single pathogenic CHEK2 variant is 20–44%." (PMID 32570972, 2020). "Although ER+ tumors tend to have a better prognosis in unselected breast cancer patients, ER+ tumors in CHEK2 mutation carriers were associated with worse breast cancer-specific survival." (PMID 33322746, 2020). "In this cohort, biallelic CHEK2 PV carriers had a significantly higher risk for breast cancer, were more likely to be diagnosed at or before age 50, and were more likely to have multiple primary breast cancers compared to monoallelic CHEK2 PV carriers." (PMID 31993860, 2020). "The third patient, with a CHEK2 missense mutation, c.1283C>T, is of Ashkenazi Jewish Romanian ancestry and had a family history that was notable for early-onset breast cancer of maternal lineage as well as prostate and breast cancer on the paternal side." (PMID 31125277, 2019). "Multi-gene analysis revealed the presence of a pathogenic variant in the CHEK2 gene which is associated with increased risk of breast cancer." (PMID 31159747, 2019). "Further development will require comprehensive and in-depth understanding of the CHEK2 1100delC-associated breast cancer to provide further personalized therapy." (PMID 30975222, 2019). "Germline pathogenic variants in DNA repair genes BRCA1, BRCA2, PALB2, ATM, and CHEK2 are associated with breast cancer risk." (PMID 31700994, 2019). "All three cases of CHEK2 mutations were patients with breast cancer who were diagnosed at a young age (age 38 years, 39 years, and 47 years)." (PMID 31125277, 2019). "A large study evaluating CHEK2 mutations in breast cancer patients from Poland found that CHEK2 carriers were significantly more likely to have ER+ (OR = 3.9; 95% CI = 2.7–5.4) than ER- (OR = 2.1; 95% CI = 1.3–3.3) tumors." (PMID 31379942, 2019). "CHEK2 pathogenic variants such as the c.1100delC variant are associated with breast cancer and have been characterized." (PMID 31349801, 2019). "It is well-known that the truncating mutation 1100delC of checkpoint kinase 2 (CHEK2) increases the risk of breast cancer about 2-fold." (PMID 31781505, 2019). "Pathogenic germline variants in checkpoint kinase 2 (CHEK2), which plays pivotal roles in DNA damage response and cell cycle regulation, confer an increased breast cancer (BC) risk." (PMID 31360903, 2019). "(2016) also concluded that the Ile157Thr mutation is a moderate risk mutation which confers a 1.5 fold increased risk for breast cancer compared to other CHEK2 mutations." (PMID 30152102, 2018). "A meta-analysis conducted in 26,000 patients and 27,000 controls showed that CHEK2*1100delC increases the risk of breast cancer three-to five-fold." (PMID 29682443, 2018). "The c.1100delC mutation of CHEK2 has been confirmed to confer an increased risk of breast cancer in women unselected by family history." (PMID 30256826, 2018). "CHEK2 mutation has been reported in breast cancer, colorectal cancer, malignant melanoma, and bladder cancer." (PMID 29682443, 2018). "In our previous study, breast cancer patients with CHEK2 mutation were characterized by older age, history of gastric cancer in family, and lower stage of disease." (PMID 29682443, 2018).